FOXO4 (forkhead box O4)
Diseases named in the same sentence as FOXO4 in open-access papers (continued):
Sharing a sentence is not in itself a finding about the gene and the disease.
non-small cell lung carcinoma (8 papers, 2016 to 2024). A group of at least three distinct histological types of lung cancer, including non-small cell squamous cell carcinoma, adenocarcinoma, and large cell carcinoma. "In metastatic non-small cell lung cancer specimens and cell lines, miR-150 levels are significantly increased and target FOXO4 (Forkhead box protein O4)." (PMID 37924077, 2023). "Furthermore, miR-150-5p has been demonstrated to play a significant role in the metastatic progression of non-small cell lung cancer by targeting FOXO4." (PMID 39449798, 2024). "Furthermore, the involvement of miR-150-5p in promoting metastatic processes in non-small cell lung cancer by targeting FOXO4 has been proven." (PMID 37627176, 2023). "FOXO4 low-level expression is found in non-small cell lung cancer and may contribute to EMT." (PMID 37924077, 2023).
rhabdomyosarcoma (8 papers, 2011 to 2025). A rare aggressive malignant mesenchymal neoplasm arising from skeletal muscle. "In humans, FOXOs were originally discovered in rhabdomyosarcomas and acute myeloid leukemias, in which three members (FOXO1, FOXO3 and FOXO4) were identified due to the chromosomal translocations that produce fusion proteins." (PMID 30646603, 2019). "While little is known about the molecular mechanisms of CIC::FOXO4 fusion oncoproteins, FOXO4 (also known as AFX) and FOXO1 (also known as FKHR) chimeras have been identified in MLL-rearranged acute leukemia (AFX::MLL) and alveolar rhabdomyosarcoma (PAX3::FOXO1)." (PMID 38882060, 2024). "The mammalian Forkhead box O (FoxO) family includes four members expressed nearly in all tissues: FoxO1 (forkhead in rhabdomyosarcoma, FKHR), FoxO3 (forkhead in rhabdomyosarcoma like protein 1, FKHRL1), FoxO4 (acute leukemia fusion gene located in chromosome X, AFX), and FoxO6." (PMID 32244542, 2020). "FOXO4, a forkhead family transcription factor, has been described as an uncommon fusion partner to MLL in acute leukemias and as a rare PAX-gene fusion partner in rhabdomyosarcoma." (PMID 25010205, 2014). "The FOXO (Forkhead box, class O) is a subfamily of forkhead transcription factor and consists of FOXO1A (FKHR: Forkhead in rhabdomyosarcoma, also known as FOXO1), FOXO3A (FKHR-like 1), MLLT7 (AFX: acute-lymphocytic-leukaemia-1 fused gene from chromosome X, also known as FOXO4) and FOXO6." (PMID 21696576, 2011).
colon carcinoma (7 papers, 2012 to 2020). "Demonstrating the importance of this pathway, forced expression of CK1α phospho-acceptor site mutant of FOXO4 (FOXO4S265/268A) potently halted the growth of RAS-mutant colon cancer cells by inducing apoptosis." (PMID 28945225, 2018). "We show that compared to β-catenin knockdown, Tcf-4 knockdown significantly inhibits cell proliferation, induces cell apoptosis, and enhances the chemosensitivity of colon cancer cells through the upregulation of FOXO4 transcriptional activity." (PMID 23029137, 2012). "Similarly, FOXO4 protein abundance increased upon siRNA depletion of CK1α or pharmacological inhibition of CK1α by D4476 in another RAS-mutant colon cancer cell line, SW480." (PMID 28945225, 2018). "Moreover, cGMP-dependent protein kinase (PKG) inhibits TCF signaling in colon cancer cells by blocking β-catenin expression and activating FOXO4." (PMID 23029137, 2012). "Therefore, we hypothesize that the upregulation of FOXO4 activity is responsible for the greater efficacy of Tcf-4 shRNA effects in colon cancer cells compared to β-catenin shRNA." (PMID 23029137, 2012). "To examine and confirm the relationship among CSN6, COP1, and FOXO4 in human cancers, we performed IHC staining on a tissue microarray (TMA) from our human colon cancer cohort to assess the expression of these proteins." (PMID 33101846, 2020). "FOXO1, FOXO3, and FOXO4 were significantly underexpressed in tumour samples: in breast, bladder and colon tumours for FOXO1, in breast tumours for FOXO3, and in breast, bladder, and colon tumours for FOXO4." (PMID 29484124, 2018). "We further demonstrate that CK1α-dependent phosphorylation of FOXO4 at serine residues 265 and 268 is necessary for 26 S proteasome-mediated FOXO4 proteolysis in the nuclei of K-RAS-mutant colon cancer cells." (PMID 28945225, 2018). "Studies have shown that cGK indirectly activates FoxO4 through activation of the JNK pathway, which provides anti-tumor effects in colon cancer cells." (PMID 22393355, 2012). "The results of CAPE obtained in C. elegans differed from the results obtained in Hct116 colon carcinoma cells: CAPE also caused strong antioxidative effects in the mammalian cells, but no activation of the FoxO4 signalling pathway was detectable." (PMID 24964141, 2014).
hepatocellular carcinoma (7 papers, 2016 to 2024). A malignant tumor that arises from hepatocytes. "In line with our findings, FOXO4 found to be aberrantly activated in both hepatocellular carcinoma tissues and cell lines, functions as an oncogene in this cancer and promotes cell proliferation while attenuating apoptosis." (PMID 34061461, 2021). "Additionally, CCDC50 promotes tumor cell proliferation by inhibiting c-Myc ubiquitin-mediated degradation and also contributes to the development of hepatocellular carcinoma through the Ras/Foxo4 signaling pathway." (PMID 38515748, 2024). "SRSF3 also affects the expression of spliced variant coiled-coil domain containing 50 short (CCDC50S) to contribute to the growth and metastasis of hepatocellular carcinoma (HCC) through the Ras/Foxo4 signaling pathway." (PMID 35198444, 2022).
prostate carcinoma (7 papers, 2014 to 2025). A carcinoma that arises from epithelial cells of the prostate gland. "Target genes of differentially methylated enhancers were notably enriched in developmental pathways, various gene sets of known transcription factor (TF) targets (ETS2 proto-oncogene, FOXO4 tumour suppressor), and in prostate cancer-associated pathways (Dataset EV14)." (PMID 41057544, 2025). "Correlation analysis showed that FOXO4 and circPDE5A were positively correlated in prostate cancer tissues." (PMID 35650605, 2022). "Although FOXO4 down-regulation is reported to correlate with reduced prostate cancer metastasis-free survival, conversely FOXO4 knockdown in LNCaP cells can increase metastatic potential." (PMID 32630372, 2020). "Thus, future work addressing the role of FOXO4 during prostate cancer progression is warranted." (PMID 32630372, 2020). "In prostate cancer, FOXO4 was identified as a metastasis suppressor gene without affecting prostate cancer proliferation." (PMID 35650605, 2022).
colitis (6 papers, 2020 to 2025). Inflammation of the colon. "Among its key components, FoxO4 functions as a crucial transcription factor that modulates immune activity and has demonstrated protective effects in experimental models of colitis." (PMID 41394814, 2025). "Another research showed that the NF-κB activity was influenced by a transcription factor forkhead box o4 (Foxo4) in vivo, which reduced in the model of TNBS-induced colitis or in IBD patients." (PMID 37564207, 2023). "In colitis mice, the expressions of SIRT1, FOXO1, FOXO3α, and FOXO4 could be increased by salidroside to attenuate inflammation reaction." (PMID 35479323, 2022). "Meanwhile, our prediction results showed that ICA may alleviate colitis through multiple oxidative stress-related signaling pathways, such as AMPK, PI3K/AKT, HIF, Foxo4." (PMID 35754510, 2022).
diabetes (6 papers, 2011 to 2023). "Foxo1 and Foxo4 upregulation was implicated in diabetes, diabetic complications and cardiovascular disease, through impairing proliferation and differentiation, and abnormal cytokine expression, inflammation, and resistance to oxidative stress." (PMID 29995913, 2018). "We demonstrated in this study that alteration in the acetylation status of a transcription factor, Foxo4, is linked to a reduction in the expression of Sirt1 and contributes to the development of podocyte loss in diabetes." (PMID 21858169, 2011). "Strategies to preserve Sirt1 expression or reduce Foxo4 acetylation could be used to prevent podocyte loss in diabetes." (PMID 21858169, 2011). "Together, our data provide evidence that alteration of Foxo4 acetylation and down regulation of Sirt1 expression in diabetes promote podocyte apoptosis." (PMID 21858169, 2011). "We also observed that 0.6% of tests had significantly different expression patterns across tissues, e.g., expressions of the FOXO4 gene set between blood (study 7) and adipocytes (study 23), indicating that the candidate gene sets also have tissue-specific roles in diabetes pathogenesis." (PMID 29503662, 2018). "In mice, conditional deletion of FoxO1, FoxO3, and FoxO4 was found to affect formation of hematopoietic stem cells and neural stem/progenitor cells, and compromised pancreatic β cell function, leading to maturity-onset diabetes of the young (MODY)-like diabetes." (PMID 37240290, 2023). "Therefore, the component gene of NPAS3 and TFs of FOXO4 and POU2F1 can form another hypothesis of potential genetic pathways related to diabetes pathogenesis." (PMID 25898945, 2015). "Even though our study suggests that Sirt1 expression and Foxo4 acetylation is altered in diabetes, we have not excluded the possibility that other targets of Sirt1 might also play a role in podocyte apoptosis." (PMID 21858169, 2011).
lung carcinoma (6 papers, 2016 to 2023). "For example, FBLN1 and FOXO4, well-known lung cancer suppressor genes, showed significantly lower expression in the A549 cells than in the BEAS-2B cells (log2 fold change < −1 and adjusted P value < 0.01)." (PMID 36702236, 2023). "Expression of miR-150 is often deregulated in lung cancer, and it was shown to promote metastasis and proliferation of cancer cells by targeting FOXO4 and SRC kinase signalling inhibitor 149–51." (PMID 29679068, 2018). "However, there has been very little research on the role of FOXO4 in lung cancer and whether FOXO4 has any metastasis effects in NSCLC remain unclear." (PMID 27976702, 2016). "For example, in lung cancer, miRNA-150 was shown to enhance tumor cell metastasis and induce EMT by targeting FOXO4." (PMID 33848981, 2021).
sarcoma (6 papers, 2017 to 2025). A usually aggressive malignant neoplasm of the soft tissue or bone. "Moreover, CIC fusion to non-DUX4 genes such as FOXO4, NUTM1, and NUTM2A seems to lead to histology and features similar to those with CIC-DUX4, although CIC-LEUTX sarcomas are related to CD31 and ETS-related gene expression." (PMID 31676869, 2019).
atherosclerosis (5 papers, 2023 to 2025). A disease characterized by the build-up of fatty material and calcium deposition in the arterial wall resulting in partial or complete occlusion of the arterial lumen. "Myeloid-specific FoxO KO (FoxO1, FoxO3a, and FoxO4), which was elevated in atherosclerotic mice’ macrophages, surprisingly worsened atherosclerosis by stimulating bone marrow cell growth." (PMID 40141412, 2025). "MiR-148a-3p was selectively upregulated in patients with atherosclerosis and its overexpression promoted proliferation and migration, while inhibiting apoptosis via FOXO4 and FOXO3 modulation, as well as counteracted the release of inflammatory factors in endothelial cells." (PMID 38791128, 2024). "Furthermore, forkhead box O4 (FOXO4) promotes VSMC migration and dedifferentiation, thereby exacerbating the progression of atherosclerosis." (PMID 39595622, 2024). "Although these isoforms have overlapping functions, single-knockout mice express distinct phenotypes;50 for instance, atherosclerosis was not suppressed in FoxO4-systemic knockout mice." (PMID 37520709, 2023).
cholangiocarcinoma (5 papers, 2014 to 2024). A carcinoma that arises from the intrahepatic biliary tree (intrahepatic cholangiocarcinoma) or from the junction, or adjacent to the junction, of the right and left hepatic ducts (hilar cholangiocarcinoma). "EGF-mediated FOXO4 phosphorylation in cholangiocarcinoma leads to the transcriptional inhibition of ANXA8, FAK downregulation, and alteration of F-actin kinetics." (PMID 31474227, 2019). "Nevertheless, recent studies have shown that FOXO4 is also a tumor promoter; for example, the upregulated FOXO4 could inhibit the invasive and metastatic characteristics of cholangiocarcinoma cells by regulating focal adhesion kinase and F-actin dynamics." (PMID 34631691, 2021). "For FOXO4, ANXA8 is transcriptionally down-regulated by EGF-mediated FOXO4 phosphorylation, which is correlated with the morphologic changes of EMT in the cholangiocarcinoma cells." (PMID 27976702, 2016).
glioma (5 papers, 2011 to 2025). A benign or malignant brain and spinal cord tumor that arises from glial cells (astrocytes, oligodendrocytes, ependymal cells). "AQP1 may be implicated in glioma formation by interacting with the transcriptional regulation networks involving the FOXO4, MAZ, and E2F1/2." (PMID 38057925, 2023). "AQP1 overexpression in rat C6 glioma CSCs enhanced cell viability and migration, potentially promoting glioma progression through transcriptional networks involving Foxo4, Maz, and E2F factors." (PMID 40806720, 2025). "Through transcriptomic analysis, we identified that AQP1 overexpression may enhance glioma tumorigenesis by influencing the transcriptional regulation networks involving Foxo4, Maz, and E2F families." (PMID 38057925, 2023). "Substrates affected include FOXO transcription factors (FOXO3 and FOXO4) and BCL-2 protein family (BAD, BCL2, and BCL2L1) in which the phosphorylated state may ensure glioma cell survival under stressful environments." (PMID 21955618, 2011).
pancreatic cancer (5 papers, 2010 to 2023). "Pancreatic cancer PANC-1 and MIA PaCa-2 cells were stably transfected with plasmids expressing FOXO1, FOXO3a and FOXO4 shRNA." (PMID 21980390, 2011). "The inhibitory effects of SFN on cell viability were further enhanced when pancreatic cancer cells were transfected with FOXO1, FOXO3a, and FOXO4." (PMID 20642839, 2010). "In order to examine whether FOXO transcription factors affect the ability of SFN to inhibit cell viability, pancreatic cancer cells were transfected with FOXO1, FOXO3a or FOXO4." (PMID 20642839, 2010).
aortic aneurysm (4 papers, 2022 to 2025). A ruptured aneurysm located in the wall of the proximal portion of the descending aorta proceeding from the arch of the aorta. "Of interest, the decreased miR-23b also promotes aortic aneurysm formation by increasing the transcription of FOXO4 (transcription factor forkhead box 4) involved in SMC phenotyping switching." (PMID 36834577, 2023). "Coronary or aortic aneurysms are important complications of KD; therefore; FOXO4 might have a protective role in the progress of KD." (PMID 36700213, 2022). "Although the underlying mechanisms remain unclear, recent research indicates the pivotal role of the XBP1u‐FoxO4‐myocardin axis in maintaining the VSMC contractile phenotype and preventing phenotypic switching during aortic aneurysm formation." (PMID 41497804, 2025). "Subsequently, FoxO4 triggered genes expression promoted proinflammatory and proteolytic phenotypic transitioning of VSMC in vitro, and resulted in dedifferentiated VSMC and aortic aneurysm formation in a mouse aneurysm model." (PMID 35173538, 2022).
hemangioma (4 papers, 2015 to 2022). A benign vascular lesion characterized by the formation of capillary-sized or cavernous vascular channels. "We and others previously showed that mice somatically depleted of FOXO1 along with its 2 close paralogs, FOXO3 and FOXO4, are predisposed to the development of thymic lymphomas and hemangiomas." (PMID 36282572, 2022). "It has been reported that conditional deletion of FoxO1, FoxO3 and FoxO4 simultaneously results in the development of hemangiomas and thymic lymphomas, and IκB kinase represses FoxO3a activity to promote human breast tumorigenesis and acute myeloid leukemia (AML)." (PMID 26474173, 2015). "In animal experiments, mice without somatic cells of FOXO1, FOXO3a, and FOXO4 led to the progression of hemangiomas and thymic lymphomas, which proved the possible function of FOXO to serve as the redundant inhibitors of tumor growth." (PMID 29221208, 2017).
liver cancer (4 papers, 2017 to 2024). An epithelial or non-epithelial malignant neoplasm that arises from the liver. "This phosphorylation is a molecular switch for hTERT to display RNA-dependent RNA polymerase (RdRP) activity, and the activity of hTERT RdRP can prevent the expression of some tumour suppressor genes, such as Forkhead box O4 (FOXO4), which can lead to pancreatic and liver cancer." (PMID 38594465, 2024).
lymph node metastasis (4 papers, 2014 to 2023). "FOXO4 expression was negatively associated with tumor diameter and the presence of lymph node metastasis." (PMID 33463054, 2021). "In cancer cells, FoxO4 is more prone to low expression, and its expression is negatively correlated with the presence of lymph node metastasis and tumor diameter." (PMID 37240290, 2023).
myocardial infarction (4 papers, 2018 to 2022). Gross necrosis of the myocardium, as a result of interruption of the blood supply to the area, as in coronary thrombosis. "In the context of post-myocardial infarction, endothelial-specific depletion of FoxO4 improved cardiac function by preventing loss of nitric oxide production." (PMID 31921839, 2019). "FOXO4 suppresses the transcription of USP10 to boost acute myocardial infarction." (PMID 35196182, 2022). "For instance, Arg1 transcription is activated by FOXO4 in myocardial infarction." (PMID 35196182, 2022). "It is then appealing to hypothesize that the interaction between MDM2 and FoxO4 in the endothelium controls the inflammatory response after myocardial infarction; a hypothesis that remains unverified." (PMID 31921839, 2019).
acute myeloid leukemia (3 papers, 2015 to 2022). Acute myeloid leukemia (AML) is a group of neoplasms arising from precursor cells committed to the myeloid cell-line differentiation. "Given that FOXO4 and FOXP3 were highly expressed in combination in precursor T lymphoblastic leukemia, acute promyelocytic leukemia, leukemia, and acute myeloid leukemia, we explored the correlation of these two genes in the GEPIA2 database and found that they were positively correlated in AML." (PMID 36292640, 2022).